STYK1 (STY kinase 1)
Diseases named in the same sentence as STYK1 in open-access papers (continued):
Sharing a sentence is not in itself a finding about the gene and the disease.
bladder cancer (2 papers, 2021). "This study showed that the lncRNA lnc-STYK1-2 encoded by the STYK1 gene serves as an essential tumor suppressor factor in bladder cancer, supported by enhanced proliferation, migration, invasion, and tumorigenesis induced by lnc-STYK1-2 silencing." (PMID 34332611, 2021). "Also, the pathogenic roles of lnc-STYK1-2 in bladder cancer were further studied using in vitro and in vivo assays, followed by identifying its interacting microRNAs and downstream signaling pathways." (PMID 34332611, 2021). "lnc-STYK1-2 inhibited bladder cancer cell proliferation, migration, and tumorigenesis by targeting miR-146b-5p to regulate ITGA2 expression and AKT/STAT3/NF-kB signaling." (PMID 34332611, 2021). "lnc-STYK1-2 silencing effectively promoted proliferation, migration, and invasion in two bladder cancer cell lines, 5637 and T24, and their tumorigenesis in nude mice." (PMID 34332611, 2021). "Together, these results revealed that ITGA2 and AKT/NFκB/STAT3 signaling pathways were regulated by lnc-STYK1-2 and miR-146b-5p in bladder cancer cells." (PMID 34332611, 2021). "This study confirmed the direct association of lnc-STYK1-2 with miR-146b-5p by dual-luciferase activity, further supported by the elevated miR-146b-5p expression in bladder cancer cells with lnc-STYK1-2 silencing." (PMID 34332611, 2021). "We then subsequently addressed the possible mediating roles of miR-146b-5p in lnc-STYK1-2-regulated bladder cancer cell functions." (PMID 34332611, 2021). "Together, these results proved that the regulation of bladder cancer cell proliferation, migration, and invasion by lnc-STYK1-2 was mediated by directly binding the miR-146b-5p." (PMID 34332611, 2021). "To further validate the function of differential expression of lnc-STYK1-2 in bladder cancer, we first detected its expression in multiple bladder cancer cell lines." (PMID 34332611, 2021). "We found that the bladder cancer cell lines T24 and 5637 possessed relatively higher levels of lnc-STYK1-2 expression." (PMID 34332611, 2021). "Considering the essential functions of lnc-STYK1-2 and miR-146b-5p interaction revealed here in bladder cancer cells, their potential for future applications in diagnosing or treating patients with cancer requires further evaluation through large-scale pre-clinical experiments." (PMID 34332611, 2021). "Also, ITGA2 expression and phosphorylation of AKT, STAT3, and p65 proteins in bladder cancer cells were greatly enhanced by silencing of lnc-STYK1-2 expression." (PMID 34332611, 2021). "Finally, treatment with miR-146b-5p inhibitors greatly abrogated the regulatory effects of lnc-STYK1-2 silencing on bladder cancer cell proliferation, migration, and invasion." (PMID 34332611, 2021). "Among them, we observed that the expression of lnc-STYK1-2 in bladder cancer tissues was greatly downregulated compared with that in adjacent tissues, which were further validated by quantitative RT-PCR (qRT-PCR) in another 16 bladder cancer tissues." (PMID 34332611, 2021). "Furthermore, knockdown of lnc-STYK1-2 expression significantly promoted the proliferation, migration, and invasion of bladder cancer cells and the tumorigenic capacity of cancer cells in nude mice." (PMID 34332611, 2021). "This in vivo assay persuasively showed that silencing of lnc-STYK1-2 expression could significantly enhance the tumorigenic capacities of bladder cancer cells." (PMID 34332611, 2021). "Regarding molecular mechanism, we further showed that lnc-STYK1-2 could directly bind with and suppress the expression of miR-146b-5p in bladder cancer cells." (PMID 34332611, 2021). "However, little is known about the roles of STYK1 in bladder cancer development." (PMID 34332611, 2021). "For more understanding of the molecular mechanisms downstream of lnc-STYK1-2 and miR-146b-5p, we analyzed the influence of lnc-STYK1-2 and its suppression of miR-146b-5p on the expression of ITGA2 and AKT/NFκB/STAT3 axis activation in bladder cancer cells." (PMID 34332611, 2021).
bladder cancer (continued). "Among them, the expression of lnc-STYK1-2 was greatly downregulated in bladder cancer tissues compared with that in adjacent noncancerous tissues." (PMID 34332611, 2021). "Alterations in lncRNA profiles, including decreased lnc-STYK1-2 expression, were detected in bladder cancer tissues compared with adjacent noncancerous tissues." (PMID 34332611, 2021). "lnc-STYK1-2 siRNA promoted miR-146b-5p and reduced ITGA2 expression in bladder cancer cells." (PMID 34332611, 2021).
breast carcinoma (2 papers, 2017 to 2022). "Based on these data, we speculated that lncRNA00544 might in part function as a tumor oncogene in HR + HER2− breast cancer via the STYK1 gene and the PI3K/AKT pathway." (PMID 28959047, 2017).
cervical carcinoma (2 papers, 2016 to 2022). A carcinoma arising from either the exocervical squamous epithelium or the endocervical glandular epithelium. "STYK1 was previously shown to cause GSK-3β (Ser9) phosphorylation via activating AKT phosphorylation at the Thr308 residue in cervical cancer Hela cell." (PMID 27628214, 2016).
ovarian carcinoma (2 papers, 2009 to 2024). A malignant neoplasm originating from the surface ovarian epithelium. "Ovarian cancer samples overexpress a putative serine-threonine receptor protein kinase, STYK1, as demonstrated by microarray analysis." (PMID 19845955, 2009). "Many of the ovarian cancer tissue sections had weak STYK1 staining intensity as seen in the benign tissues, however, moderate and strong STYK1 staining intensity was seen only in the malignant ovarian tissues (i.e. endometroid adenocarcinomas)." (PMID 19845955, 2009). "We conclude that STYK1 is expressed in ovarian cancer and is regulated by estrogen through a GPR30 hormone-signaling pathway, to the exclusion of estrogen receptor-alpha." (PMID 19845955, 2009). "Moreover, benign and ovarian cancer cell lines expressed STYK1 as determined by RT-PCR." (PMID 19845955, 2009).
bone osteosarcoma (1 paper, 2025). A usually aggressive malignant bone-forming mesenchymal neoplasm arising from the bone. "Furthermore, we further determine the effects of STYK1 on GSK3β sequestration in ATG7–/– human bone osteosarcoma epithelial cells (U2OS cell line)." (PMID 40588478, 2025).
gallbladder cancer (1 paper, 2022). "Oncogenic potential of STYK1 has been studied widely in gallbladder cancer (GBC) and was reported to be largely dependent on the PI3K/AKT pathway." (PMID 35884586, 2022).
lung adenocarcinoma (1 paper, 2023). A carcinoma that arises from the lung and is characterized by the presence of malignant glandular epithelial cells. "Secondly, specific proteins in lung adenocarcinoma cells, such as NFS1, STYK1, and LSH, play important regulatory roles in the process of ferroptosis." (PMID 37946181, 2023).
lymph node metastasis (1 paper, 2017). "STYK1 was positively correlated with lymph node metastasis (P=0.009) and clinical stage (P=0.03) while other clinico-pathological features such as age, gender, and tumor location were not correlated with its expression." (PMID 29340057, 2017).
metastasis (1 paper, 2017). The spread or migration of cancer cells from one part of the body (where they first appeared) to another. "Univariate survival analysis revealed that, in addition to tumor differentiation, lymph node metastasis, and tumor stage, high STYK1 expression predicted poor prognosis (P<0.05)." (PMID 29340057, 2017).
squamous cell carcinoma (1 paper, 2021). A carcinoma arising from squamous epithelial cells. "We observed that STYK1 mRNA level was upregulated in 5 squamous cell carcinomas and 5 adenocarcinomas, which was consistent with ONCOMINE data." (PMID 34295886, 2021).
tumor (20 papers, 2009 to 2025). "The growth curve and weight of dissected tumor further confirmed the progress of tumor cell growth caused by STYK1 overexpression." (PMID 27628214, 2016). "Moreover, the Wnt signaling inhibitor XAV939 and autophagy inhibitor CQ both suppressed STYK1-mediated xenograft tumor growth, including mutant variants." (PMID 40588478, 2025). "In addition, we found that PAX3-FOXO1 regulates the expression of STYK1, which is also associated with tumor invasion and metastasis, although molecular targeted therapy against STYK1 is not developed." (PMID 34552155, 2021). "Overexpression of STYK1 was significantly associated with increased cell proliferation, migratory capability, and invasive capability in vitro, as well as increased volume of tumor, weight of tumor, and number of pulmonary metastases in vivo." (PMID 27628214, 2016). "From the in vivo proliferation analysis, we found STYK1 Y191D enhanced tumor growth, while Y191F or SS1/2/3 attenuated progression in PANC-1 xenografts." (PMID 40588478, 2025). "Tumor burden assessments (volume and weight) revealed substantial reductions in STYK1-depleted groups compared to shRNA-control implants." (PMID 40588478, 2025). "STYK1 depletion-induced down-regulation of Wnt/β-catenin target genes was further confirmed by IHC staining of the xenograft tumor tissues." (PMID 40588478, 2025). "We found that depletion of STYK1 in mouse xenograft models resulted in markedly attenuated tumor growth kinetics relative to control cohorts." (PMID 40588478, 2025). "SPINT2 is a serine protease inhibitor where decreased expression facilitated STYK1-mediated tumor progression." (PMID 38260835, 2023). "Even though LPS treatment failed to diminish the expression of genes involved in proliferation and malignancy such as GEN1, KRIT1, CENPF, STYK1, and Sam68/KHDRBS3, it did reduce the expression of numerous genes implicated in tumor growth." (PMID 35884586, 2022). "The tumor-stimulating activity of STYK1 was abolished by the AKT-specific inhibitor MK2206 as well as by STYK1 gene silencing." (PMID 35884586, 2022). "The results of in vivo imaging revealed that 4 weeks after tail vein injection of tumor cells, mice harboring STYK1 overexpressing SW900 cells had more metastatic sites and emitted more photons than mice injected with wild-type cells." (PMID 34295886, 2021). "Taken together, our studies verified that STYK1 functioned as a tumor promoting factor through enhancing NSCLC cell growth and metastasis." (PMID 31164631, 2019). "The elevated STYK1 expression was positively correlated to tumor size, tumor invasion, distant metastasis, differentiation, and AJCC 8th stage." (PMID 31164631, 2019). "Consistently, the IHC analysis results indicated that elevated STYK1 expression was positively correlated to NSCLC tumor size and tumor invasion." (PMID 31164631, 2019). "Both STYK1 and E-cadherin expression pattern were significantly different between tumor and normal tissue samples." (PMID 29340057, 2017). "Kaplan-Meier analysis indicated that high E-cadherin and low STYK1 expression in tumor samples favored good clinic outcomes." (PMID 29340057, 2017). "In conclusion, we demonstrated that STYK1 is highly expressed in tumor tissues and is significantly correlated with poor outcome of HCC." (PMID 27628214, 2016). "Further correlation analyses suggested that STYK1 overexpression correlated with tumor size, vascular invasion, and higher TNM stage." (PMID 27628214, 2016). "STYK1 overexpression was significantly correlated with tumor size, vascular invasion, and a higher tumor-nodule-metastasis (TNM) stage." (PMID 27628214, 2016). "Functional studies demonstrated that STYK1 has the ability to promote cell proliferation, induce transformation and tumorigenesis and facilitate tumor cell invasion and metastatic progression." (PMID 25884558, 2015).
tumor (continued). "STYK1 expression was frequently up-regulated in CRC clinical samples at the protein levels and was significantly associated with tumor differentiation grade (p = 0.030), lymph node metastasis (p = 0.004), TNM stage (p = 0.007) and patient death (p < 0.001)." (PMID 25884558, 2015). "STYK1 is overexpressed in CRPC, and STYK1 knockdown can inhibit the growth of tumor cells, which may be a molecular target of CRPC." (PMID 38887275, 2024). "Our data also demonstrate that blocking STYK1/NOK ameliorates mitotic defects, suggesting that therapeutic targeting STYK1/NOK may represent a novel approach in preventing STYK1/NOK-associated tumor progression and metastasis." (PMID 36506394, 2022). "STYK1 shares 20-30% homology with fibroblast and platelet-derived growth factor receptors and has been reported to display cellular-transforming capabilities and enhance tumor progression by promoting invasion and metastasis." (PMID 35840561, 2022). "Moreover, STYK1 depletion also contributed to the downregulation of Ki67 in xenograft tumor tissues." (PMID 37192859, 2022). "Given STYK1’s roles in promoting angiogenesis and changing the vascular morphology during tumor growth, it is deduced that STYK1 may have an effect on the remodeling of blood vessels in the brain." (PMID 35478846, 2022). "Firstly, the STYK1 degradation might be reduced in tumor cell lines compared to that in HBE cells because of the UPS-SUMOylation imbalance." (PMID 34295886, 2021). "Therefore, we performed the supplementary RT-qPCR to test the STYK1 mRNA level in tumor samples and corresponding normal lung tissues of some patients included in the study." (PMID 34295886, 2021). "Moreover, NSCLC patients with deep tumor invasion (T3/T4) and high AJCC 8th stage (stages III/IV) had higher expression of STYK1 than these with superficial tumor invasion (T1/T2) and low AJCC 8th stage (stages I/II) (P < 0.001)." (PMID 31164631, 2019). "Additionally, the promotion of tumor growth by STYK1 was further confirmed in subcutaneous xenograft tumor nude mice model." (PMID 31164631, 2019). "Besides, STYK1-mediated acceleration of tumor cell migration and EMT were dependent on MEK/ERK and PI3K/AKT signaling." (PMID 29340057, 2017). "In contrast, high levels of STYK1 were detected in tumor tissues on both cytoplasm and membrane." (PMID 29340057, 2017). "HCC tissues expressed greater levels of STYK1 than paired non-tumor tissues." (PMID 27628214, 2016). "Overall, these results suggest that STYK1 promoted tumor invasion and metastasis by inducing EMT." (PMID 27628214, 2016). "Serine/threonine/tyrosine kinase 1 (STYK1) is known to be involved in tumor progression." (PMID 27628214, 2016). "Furthermore, we investigated if MEK/ERK and PI3K/AKT signaling are responsible for STYK1-mediated acceleration of tumor cell migration, invasion, and EMT." (PMID 27628214, 2016). "In the present study, we evaluated the phenotypic expression of STYK1 protein immunohistochemically in a large number of CRC clinical samples and examined the correlation of STYK1 expression with clinicopathologic features and with patient survival based on tumor stage." (PMID 25884558, 2015). "Interestingly, while LPS treatment increased the proliferation and expression of the GEN1, KRIT1, CENPF, CPLANE1, STYK1, and KHDRBS3 genes, it decreased the expression of the cancer associated LOC610994, Gpatch4, SLC7A1, ATP13A2, and TEX45 genes in tumor enteroids." (PMID 35884586, 2022). "It is also possible that LPS-induced enhanced proliferation in tumor enteroids was caused by the increased expression of genes involved in the cell cycle process such as centromere protein F (CENPF) and flap endonuclease GEN homolog 1 (GEN1) as well as a receptor protein tyrosine kinase (STYK1)." (PMID 35884586, 2022). "Secondly, STYK1 inhibition of non-coding RNAs might be weaker in tumor cell lines than that in HBE." (PMID 34295886, 2021).
tumor (continued). "Then we investigated whether SPINT2 involves in STYK1-mediated tumor progression." (PMID 31164631, 2019). "Thus, as an oncogene, STYK1 could be a candidate biomarker for tumor diagnosis and prognosis prediction." (PMID 25884558, 2015). "Our results agree with previously published studies indicating that increased STYK1 expression correlates with enhanced tumor growth and invasiveness in NSCLC and with poorer prognosis for NSCLC patients, making STYK1 also a potential prognostic marker." (PMID 35840561, 2022). "A crucial NF-κB regulator, Sam68 (KHDRBS3), was also observed to be elevated in LPS-treated tumor enteroids, along with the genes GEN1, KRIT1, CENPF, and STYK1." (PMID 35884586, 2022). "We verified that elevated serine threonine tyrosine kinase 1 (STYK1) or decreased serine peptidase inhibitor Kunitz type 2 (SPINT2/HAI-2) expression significantly correlated with poor prognosis, tumor invasion, and metastasis of NSCLC patients." (PMID 31164631, 2019). "After verifying the relation between STYK1 and its downstream target SPINT2, we further detected the SPINT2 expression by IHC tissue array analysis containing 347 paired tumor-normal samples." (PMID 31164631, 2019). "To further verify the action of STYK1 overexpression on promoting NSCLC cell proliferation, we then established H1299 cell xenograft in athymic nude mice and measured their tumor volumes." (PMID 31164631, 2019). "It was shown that there was a noticeable STYK1/NOK over expression in CRC tissues and a significant correlation between STYK1/NOK over expression and tumor size." (PMID 30579343, 2018). "Immunohistochemical staining revealed the presence of STYK1 at significant levels in HCC tissues and relatively insignificant levels in paired, non-tumor tissues." (PMID 27628214, 2016). "Serine-threonine tyrosine kinase 1 (STYK1), also known as a novel oncogene with kinase domain (NOK), belongs to the receptor protein tyrosine kinases (RPTKs) subfamily, and has a strong ability to promote tumor formation and metastatic capacity." (PMID 37005430, 2023). "Interestingly, the downregulation of STYK1 alone also compromised colony growth similarly to the EGFR TKI, indicating that STYK1 acts as a tumor-promoting factor in EGFR-mutant cells." (PMID 35840561, 2022). "Our study lends credence to the notion that indeed, STYK1/NOK is regulated during cell division and that deregulation of STYK1/NOK affects the central machinery of genetic transmission during mitosis, which often confers vulnerability to neoplastic transformation and tumor formation." (PMID 36506394, 2022). "Interestingly, STYK1 (with Z-scores of −2.1 and −2.67 in PC9 and HCC827, respectively) has been reported to be overexpressed in NSCLC where it contributes to tumor growth and metastasis." (PMID 35840561, 2022). "STYK1 protein was upregulated in NSCLC cells compared to its expression in HBE cells, whereas STYK1 mRNA level was surprisingly much lower in tumor cells." (PMID 34295886, 2021). "We then measured the STYK1 expression in the initial cohort of 24 paired NSCLC and adjacent noncancerous tissues by western blot, and we found the STYK1 protein expression was significantly higher in tumor (T) than that in normal (N) tissues." (PMID 31164631, 2019). "The tumor promoting effect of the HCV transgene may be explained both by upregulation of pro-tumorigenic genes as Ubd, Erbb4, Nrg1, Ndrg1, Styk1, and by evasion of host defense response by viral proteins." (PMID 19340302, 2009). "According to our results, increased expression of STYK1 protein was significantly correlated with poor tumor differentiation, increased lymph node metastasis and advanced TNM stage of the disease, indicating that STYK1 may be involved in the progression of CRC." (PMID 25884558, 2015). "This “non-basal-like non-classical” tumor subset expresses core signatures such as high TMPRSS4, SLC6A14, IFI27, CST1, and STYK1." (PMID 39774001, 2025).